E2F1 (E2F transcription factor 1)
Diseases named in the same sentence as E2F1 in open-access papers (continued):
Sharing a sentence is not in itself a finding about the gene and the disease.
lung carcinoma (continued). "Restoration of reduced miR-330 and miR-433 suppresses the proliferation and invasion of lung cancer cells by targeting the two members of transcription factor family, E2F1 and E2F3, respectively." (PMID 36303933, 2022). "For example, E2F transcription factor 1 (E2F1)-mediated transcriptional upregulation of SNHG3 in lung cancer enhanced the abilities of cell proliferation and migration by activating the TGF-β pathway and interleukin 6 (IL-6) signaling." (PMID 35030969, 2022). "Clinical studies have shown that high expression of E2F1 and CCNE1 are associated with poor prognosis in lung cancer patients." (PMID 33613291, 2021). "The novel lncRNA EMS was identified as a direct c-Myc transcriptional target that functions as an oncogenic gene by increasing E2F1 expression and promoting G1/S cell cycle progression in lung cancer cells." (PMID 34081626, 2021). "Among the 60 potential therapeutic targets, cell cycle related genes CCNE1 and E2F1 were high expression and predictive of poor patient survival in lung cancer." (PMID 33613291, 2021). "The results showed that CCNE1, E2F1, ARHGAP11A, RUNX1T1 and FES were significantly associated with patient survival in lung cancer (n = 1925)." (PMID 33613291, 2021). "We focused on E2F1 because several E2F1 binding sites displayed high scores and E2F1 have been demonstrated to be highly expressed in lung cancer and served as a tumor pro motor." (PMID 33968966, 2021). "Survival analysis showed that high expression of DMDD potential targets CCNE1 and E2F1 was significantly related to poor patient survival in lung cancer." (PMID 33613291, 2021). "It is worth noting that CCNE1 and E2F1 were high expression in lung cancer and predictive of poor patient survival." (PMID 33613291, 2021). "Recently, a novel lncRNA named E2F1 messenger RNA (mRNA) stabilizing factor (EMS) was revealed to be able to connect c-Myc to cell cycle regulation and oncogenesis through modulating the stability of E2F1 mRNA in lung cancers." (PMID 34081626, 2021). "Aspirin has been shown to inhibit the expression of E2F-1 which regulates DHFR expression in human lung cancer cells." (PMID 34866142, 2021). "In fact, previous clinical studies also showed that CCNE1 and E2F1 have a tumor promoting effect in many cancers including lung cancer." (PMID 33613291, 2021). "RUNX1 stimulated G1 to S progression in hematopoietic cells, partly via transcriptional induction of cyclin D2 promoter, whereas RUNX1 depletion resulted in an increased E2F1 mRNA levels in lung cancer cells." (PMID 32498288, 2020). "It has been reported that hsa-miR-342-3p regulates BRCA1 expression and MYC transcriptional activity by directly repressing E2F1 in human lung cancers." (PMID 32182819, 2020). "SAHA overcomes 5-FU resistance by downregulating TS expression by blocking the Rb-E2F1 pathway in lung cancer cells." (PMID 33256074, 2020). "NR4A2 and E2F1 function have been related with resisting to cell death and sustaining a proliferative signal processes in lung cancer." (PMID 31867044, 2019). "KAT2A over expression increases the extent of histone acetylation by interacting with E2F1, cyclin D1, and E1 promoters to promote the proliferation of lung cancer cell lines." (PMID 31828117, 2019). "As the expression of E2F1 was markedly regulated by GCN5 at both protein and mRNA levels in E7‐expressing cells and GCN5 was shown to bind E2F1 promoter in lung cancer cell lines, we believe that GCN5 binds E2F1 promoter in E7‐expressing cells." (PMID 30079588, 2018). "MiR-342 was shown to be a negative regulator of E2F1 affecting MYC expression in lung cancer cells and also negatively regulate FOXM1 and FOXQ1 expression in colorectal cancer cells." (PMID 29599914, 2018).
lung carcinoma (continued). "We observed that the site #1 is occupied by Flag-tagged E2F1 in two human non–small-cell lung cancer cell lines, H460 and A549." (PMID 30389914, 2018). "Among them, CTNNB1, ZEB1, CDC42, HSP90AA1, BST2, PCNA, and E2F1 have all been shown to promote lung cancer progression, while SAMHD1, HRAS, and NQO1 serve as tumor suppressor genes." (PMID 28498804, 2017). "GASL1 was first identified as an E2F1-regulated lncRNA in an RNA Seq.-based screen performed using the human osteosarcoma cell line U2OS and the human lung carcinoma cell line H1299, which express conditionally active E2F1, namely ER-E2F1." (PMID 28423601, 2017). "Overall survival in lung cancer patient is known to be poorer in patients with over-expression of E2F1 or E2F2 than in those with normal expression." (PMID 29254182, 2017). "Mechanistically, XPC deficiency has been reported to increase the invasiveness of lung cancer through downregulation of p27 (kip) and upregulation of skp2 and E2F1." (PMID 25871391, 2015). "Increased E2F-1 expression correlates with a poorer outcome in certain cancers such as lung cancer, and malignant melanoma." (PMID 24658650, 2014). "Although expression of E2F1 had been detected in lung cancer tissue, its expression was inconsistent among different populations, especially in NSCLC." (PMID 24755270, 2014). "Although E2F1 expression varies in different types of lung cancer, ours together with other’s finding demonstrated that overexpression of E2F1, at least partially, contributed to invasion and metastasis in both SCLC and NSCLC." (PMID 24755270, 2014). "E2F1 is a transcriptional activator of MMP-9 that regulates lung cancer cell invasion and metastasis." (PMID 25009665, 2014). "Further investigation is required to examine the level in populations with large numbers of samples, and to clarify the relationship between E2F1 and lung cancer." (PMID 24755270, 2014). "Data obtained from microarrays, tissue samples from lung cancer patients and human lung cancer cell lines indicate that cell cycle regulatory molecules, like E2F1–5, p130, Skp2, cyclin D1 and p16, contribute to the growth and progression of lung tumors." (PMID 20421925, 2010). "Moreover, in lung cancer cells, the knockdown of KPNA2 has been shown to be associated with a subcellular redistribution of E2F1." (PMID 41413918, 2025). "Phosphatase and tensin homolog (PTEN) could bind to E2F1 to suppress E2F1-mediated transcription, and then impaired cell cycle in lung cancer." (PMID 40221814, 2025). "Interfering with the E2F1-lncRNA network could emerge as a pivotal approach for precise lung cancer therapy." (PMID 39119602, 2024). "Furthermore, overexpression of E2F1 significantly shortened overall survival (OS) in lung cancer patients observed over 200 months, while this trend was also noted in hepatocellular carcinoma (HCC) patients." (PMID 39119602, 2024). "There was a study showing that E2F1 negatively regulates CASP2 expression in lung carcinoma cells." (PMID 39524140, 2024). "Dysregulation of E2F1 has been demonstrated in a number of cancers, including lung cancer 46-51." (PMID 37705754, 2023). "RB1 can interacts with E2F1 to regulate EMT related proteins in lung cancer." (PMID 35969010, 2022).
lung carcinoma (continued). "DMDD has the potential to be an effective agent against lung cancer by inhibiting proliferation, clone formation, migration and causing cell cycle arrest at G1/S through decreasing the expression of DMDD potential targets E2F1 and CCNE2." (PMID 33613291, 2021). "In addition, SMAC can be upregulated by transcription factor E2F1 (E2F1) in lung cancer at both mRNA and protein levels." (PMID 32325691, 2020). "Potently inhibits the proliferation and clonogenic activity in lung cancer cells.Arrests cell cycle at G1 phase and up-regulates the expression of cyclin-dependent kinase inhibitor p21 in lung cancer cells.An E2F1-targeting cell cycle inhibitor, which is overexpressed in lung cancer tumor." (PMID 32397127, 2020). "Then, we proposed that SBF2-AS1 could promote lung cancer cell proliferation through the SBF2-AS1-miR-338-3p/362-3p-E2F1 axis." (PMID 31071530, 2019). "In addition, expression of SBF2-AS1 and expression of E2F1 were positively correlated in lung cancer tissues." (PMID 31071530, 2019). "In addition, a recent study shows that PTEN binds to and interacts with the E2F1 promoter region, thus regulating E2F1-mediated transcription in lung cancer." (PMID 31866820, 2019). "Furthermore, increased expression of miR-34a induced cell proliferation inhibition, cell cycle arrest and cell senescence of lung cancer cells by targeting E2F1/E2F3." (PMID 28389657, 2017). "Both KPNA2 and E2F1 are overexpressed in lung cancer and other human cancers, and the study presented here highlights that this positive feedback loop may provide a new avenue for cancer targeted therapy." (PMID 27009856, 2016). "Furthermore, the anticancer agent flavopiridol induces an increase of E2F1 protein levels that is responsible to the apoptosis in H1299 lung carcinoma cells." (PMID 24475272, 2014). "Here we detected the expression of E2F1 in lung cancer among a Chinese Han population." (PMID 24755270, 2014). "Therefore, we firstly examined E2F1 levels in human lung cancer tissues in a Chinese Han population." (PMID 24755270, 2014). "The four TFs (YY1, ZEB1, NR4A2 and E2F1) found coexpressed and identified with the DAVID-Opossum analysis have evidence of its association with tumorigenic processes, that could relate them to establishment of lung cancer." (PMID 31867044, 2019). "FTO is also recognized as a crucial gene that interferes with the m6A modification of E2F1 48, and overexpression of FTO has been found to decrease m6A levels in E2F1, highlighting its critical role in the progression of lung cancer." (PMID 41281757, 2025). "In lung cancer cells H1299 and A549, many targets of SET7/9 have been identified, including E2F1, Gli3, and Mdm2." (PMID 35069908, 2022). "E2F1, NR4A2, and ZEB1 reappear coexpressed in the LCII network, further verifying their importance for the establishment and progression of lung cancer since they are also in the LC&LD network and in the LCI network." (PMID 36101460, 2022). "E2F1, E2F2, and E2F8 are E2F family members and are overexpressed in lung cancer cells (compared to normal human lung tracheobronchial epithelial cells)." (PMID 36209131, 2022). "E2F1 and E2F3 have been shown to be overexpressed and exert tumor-promoting effects in several types of cancers including lung cancer 10, 17, 43-45." (PMID 35844795, 2022). "In lung cancer, nicotine promotes migration and stemness of non-small cell lung adenocarcinoma (NSCLC) cells via the α7 nAChR/Yap1/E2F1 axis." (PMID 36284268, 2022). "It is particularly worth noting that the decreased expression of E2F1 in asthma patients is consistent with what we have previously observed in COPD patients, which is different from that in lung cancer patients." (PMID 34136532, 2021). "Mechanistic studies showed that DMDD treatment induced G1/S cell cycle arrest by suppressing CCNE1, E2F1 and CDK2 and upregulating tumor suppressor gene p21 in lung cancer cells." (PMID 33613291, 2021).
lung carcinoma (continued). "We have identified that E2F1 and CCNE1 which are DMDD potential targets, were upregulated in lung cancer." (PMID 33613291, 2021). "In vitro experiments showed that DMDD is an effective inhibitor of E2F1 and CCNE1 and leading to the suppression of proliferation, migration and clone formation in lung cancer cells." (PMID 33613291, 2021). "Collectively, these results indicate that DMDD induces G1/S cell cycle arrest by regulating its potential targets E2F1 and CCNE1 in lung cancer cancer cells." (PMID 33613291, 2021). "Metformin down-regulated four E2F family members, E2F1, E2F2, E2F7, and E2F8 in lung cancer cells, with E2F8 being the most prominently down-regulated one." (PMID 29254182, 2017). "E2F1 expression was positive in 95.56% (86/90) of SCLC, 50% (5/10) of large lung cancer cell (LCLC), and 10% (2/20) of adenocarcinoma samples compared with the normal alveolar sections." (PMID 24755270, 2014). "To explore if E2F1 regulates expression of long non-coding RNAs (lncRNAs) we took advantage of a human osteosarcoma cell line U2OS and a human lung carcinoma cell line H1299 that each express conditionally active E2F1, namely ER-E2F1." (PMID 24168400, 2013). "These expression profiling results are supported by a drastically or even completely reduced induction of the E2F-responsive E2F-1 promoter, a reporter for S phase induction, in melanoma cells compared with HBEC and lung cancer cells." (PMID 22140489, 2011). "Notably, among the TAZ-AS202/E2F1 targets we found the EPHB2 receptor, a key protein in this pathway that is overexpressed in lung cancer cells." (PMID 37980331, 2023). "Moreover, mechanistic study clarifies that the regulation of lung cancer by NLE1 needs the participation of CDK1 as a downstream target, whose E2F1-mediated transcription was regulated by NLE1." (PMID 36818671, 2022). "In lung cancer H1299 cells, transfection of miR-449a/b has resulted in oncogenic CDK6 and CDC25A to be suppressed, leading to the dephosphorylation of pRB and decreased amount of E2F1 expression." (PMID 36303933, 2022). "Thus, combined PLK1/FGFR1 inhibition abolishes ROS homeostasis, leading to oxidative stress‐activated JNK/p38/E2F1 signaling and induction of apoptosis in KRAS‐mutant lung cancer cells." (PMID 34369083, 2021). "RB1 was directly targeted by miR-661 and could interact with E2F1 to affect EMT process and invasion lung cancer." (PMID 28716024, 2017). "This possibility was ruled out as knockdown of E6AP had no significant impact on E2F1 protein levels, consistent with our recent findings in lung cancer cells." (PMID 28477016, 2017). "In addition, E2F1 and RAP2B were reported to promote progression and metastasis of lung cancer and their expressions was downregulated by miR-342-3p in lung cancer." (PMID 27096956, 2016). "Quantification of reporter gene expression revealed that in lung cancer cells, infection with HAdV-5 induces the E2F-1 promoter, but not the SV40 promoter, much stronger than the replication-deficient virus control." (PMID 22140489, 2011). "DMDD may be used as an effective anti-lung cancer drugs by targeting CCNE1 and E2F1." (PMID 33613291, 2021). "Altogether, these results suggest that the gene module regulated by E2F1 might explain the different response to chemotherapies between smoker and non-smoker lung cancers." (PMID 24341432, 2013).
lung carcinoma (continued). "Consequently, the high expression of E2F1 and E2F2, alongside RB1 inactivation and activation of downstream oncogenes, constitutes a complex regulatory network that significantly influences the onset, progression, and prognosis of lung cancer, particularly NSCLC." (PMID 40568194, 2025). "However, cyclin D1 expression was not affected by metformin in lung cancer cells while E2F1 knockout cells showed normal proliferation in a mouse model, implying that other factors may be involved in metformin-induced cell cycle arrest in lung cancer cells." (PMID 29254182, 2017).